SNTN (sentan, cilia apical structure protein)
Description:
May be a component of the linker structure that bridges the ciliary membrane and peripheral singlet microtubules.
Synonyms: S100A1L; FLJ44379; S100AL; sentan
Tractability: No criterion of Open Targets' tractability assessment is met for any kind of drug.
Gene: Protein-coding gene on chromosome 3 (63,652,675 to 63,679,020, forward strand). Ensembl gene ENSG00000188817.
Subcellular location: Cell projection, cilium
Gene Ontology:
Molecular function: calcium ion binding; calcium-dependent protein binding; transition metal ion binding
Cellular component: cilium
Genetic constraint (gnomAD): Loss-of-function variants: 12 observed, 14.41 expected, observed/expected ratio (o/e) 0.83, 90% interval 0.53 to 1.35. The upper end of that interval is the gene's LOEUF score, 1.35, which puts it in group 5 of 6, group 1 being the genes least tolerant of losing a copy. Missense variants: 187 observed, 177.54 expected, observed/expected ratio (o/e) 1.05, 90% interval 0.93 to 1.19. Synonymous variants: 69 observed, 62.19 expected, observed/expected ratio (o/e) 1.11, 90% interval 0.91 to 1.36.
Homologues: Orthologues: chimpanzee SNTN (91% identical), dog SNTN (82% identical), pig SNTN (80% identical), rabbit SNTN (78% identical), mouse Sntn (72% identical), rat Sntn (68% identical), macaque SNTN (67% identical), guinea pig SNTN (55% identical), tropical clawed frog sntn (46% identical). Paralogues in human: S100Z (20% identical), S100A1 (19% identical), S100A2 (18% identical), S100A4 (18% identical), S100A10 (17% identical), S100A9 (16% identical), S100A7A (16% identical), CRNN (15% identical), S100A11 (15% identical), S100A7 (15% identical), S100B (15% identical), S100A14 (14% identical), and 9 more.
Diseases named in the same sentence as SNTN in open-access papers:
SNTN is named in the same sentence as 4 diseases in open-access papers, as found by Europe PMC text mining. Sharing a sentence is not in itself a finding about the gene and the disease. The quoted sentences say what the papers report.
co-infection (1 paper, 2022). "In line with this, we found mRNA levels of markers of epithelial cell differentiation to ciliated cells (transcription factor FOXJ1 and the ciliary apical structure protein SNTN) to be lower following co-infection with non-mucoid PA and HRV than after viral infection alone." (PMID 35265536, 2022). "After co-infection with HRV and the non-mucoid PA isolate, we detected lower mRNA levels of Forkhead box J1 (FOXJ1) and Cilia Apical Structure Protein (SNTN), markers of epithelial cell differentiation to ciliated cells." (PMID 35265536, 2022).
tumor (1 paper, 2019). "The common downregulated genes in metastasis and primary tumor include anterior gradient protein 3 homolog (AGR3) and Sentan cilia apical structure protein (SNTN)." (PMID 31600962, 2019).
SNTN also shares sentences with these, for which no sentence is quoted: ovarian carcinoma (1 paper); viral infection (1).